MAOA (monoamine oxidase A)
Description:
Catalyzes the oxidative deamination of primary and some secondary amine such as neurotransmitters, with concomitant reduction of oxygen to hydrogen peroxide and has important functions in the metabolism of neuroactive and vasoactive amines in the central nervous system and peripheral tissues. Preferentially oxidizes serotonin. Also catalyzes the oxidative deamination of kynuramine to 3-(2-aminophenyl)-3-oxopropanal that can spontaneously condense to 4-hydroxyquinoline (By similarity).
Synonyms: MAO-A; BRNRS
Tractability: Small molecule: an approved drug acts on it; a structure with a bound ligand is known; a high-quality ligand is known; it belongs to a druggable protein family. Antibody: UniProt predicts a signal peptide or a membrane-spanning region. PROTAC: ubiquitination databases record sites on it; its protein half-life has been measured; a small molecule that binds it is known.
Target class: Enzyme; Oxidoreductase
Chemical probes: PD082145, PD083433, PD083606
Safety:
Unwanted effects reported when the protein is acted on. In parentheses: how it was acted on, where the effect was seen, and who reports it.
dizziness (Bowes et al. (2012), Urban et al. (2012): inhibition, cardiovascular system, central nervous system; Lynch et al. (2017): inhibition, acute dosing, Pharmaco-kinetics, central nervous system)
nausea (Lynch et al. (2017): inhibition, acute dosing, Pharmaco-kinetics, central nervous system; Bowes et al. (2012): inhibition, cardiovascular system, central nervous system)
sleep disturbances (Lynch et al. (2017): inhibition, acute dosing, Pharmaco-kinetics, central nervous system; Bowes et al. (2012): inhibition, cardiovascular system, central nervous system)
weakness (Urban et al. (2012): inhibition, cardiovascular system, central nervous system; Lynch et al. (2017): inhibition, acute dosing, Pharmaco-kinetics, central nervous system)
blurred vision (inhibition; cardiovascular system, central nervous system; source: Urban et al. (2012))
decreased aggression (inhibition, acute dosing; Pharmaco-kinetics, central nervous system; source: Lynch et al. (2017))
decreased anxiety (inhibition, acute dosing; Pharmaco-kinetics, central nervous system; source: Lynch et al. (2017))
drug-drug interaction potential (inhibition; cardiovascular system, central nervous system; source: Bowes et al. (2012))
drug-drug interactions (inhibition, acute dosing; Pharmaco-kinetics, central nervous system; source: Lynch et al. (2017))
fatigue (inhibition, acute dosing; Pharmaco-kinetics, central nervous system; source: Lynch et al. (2017))
hypertensive when combined with pressor amines such as tyramine present in cheese: inhibitors may induce severe hypertensive crisis (known as \cheese reaction\) (inhibition; cardiovascular system, central nervous system; source: Urban et al. (2012))
hypomania (inhibition; cardiovascular system, central nervous system; source: Urban et al. (2012))
increased blood pressure when combined with amines such as tyramine (inhibition; cardiovascular system, central nervous system; source: Bowes et al. (2012))
serotonin syndrome (inhibition; cardiovascular system, central nervous system; source: Urban et al. (2012))
tremors (inhibition, acute dosing; Pharmaco-kinetics, central nervous system; source: Lynch et al. (2017))
Gene: Protein-coding gene on chromosome X (43,654,907 to 43,746,821, forward strand). Ensembl gene ENSG00000189221.
Subcellular location: Mitochondrion outer membrane
Subcellular location (Human Protein Atlas): Mitochondria; Cytosol
Pathways (Reactome):
Neuronal System: Dopamine clearance from the synaptic cleft; Enzymatic degradation of Dopamine by monoamine oxidase; Enzymatic degradation of dopamine by COMT; Metabolism of serotonin; Norepinephrine Neurotransmitter Release Cycle
Disease: Defective MAOA causes BRUNS
Immune System: Interleukin-4 and Interleukin-13 signaling
Metabolism: Biogenic amines are oxidatively deaminated to aldehydes by MAOA and MAOB
Gene Ontology:
Molecular function: monoamine oxidase activity; primary methylamine oxidase activity; protein binding; oxidoreductase activity
Biological process: biogenic amine metabolic process; dopamine catabolic process; phenylethylamine catabolic process; serotonin metabolic process
Cellular component: mitochondrion; mitochondrial outer membrane
Gene-disease validity (ClinGen):
ClinGen rates the evidence that MAOA causes each of these diseases.
Brunner syndrome (X-linked): Definitive.
Homologues: Orthologues: chimpanzee MAOA (99% identical), macaque MAOA (98% identical), dog MAOA (90% identical), pig MAOA (89% identical), rat Maoa (88% identical), mouse Maoa (87% identical), rabbit MAOA (82% identical), guinea pig MAOA (77% identical), tropical clawed frog maoa (67% identical), Caenorhabditis elegans spr-5 (18% identical), Caenorhabditis elegans lsd-1 (17% identical), Drosophila melanogaster CG10561 (15% identical), and 6 more. Paralogues in human: MAOB (71% identical), KDM1A (22% identical), KDM1B (20% identical), PAOX (18% identical), IL4I1 (18% identical), SMOX (17% identical), PPOX (13% identical).
Diseases named in the same sentence as MAOA in open-access papers:
MAOA is named in the same sentence as 226 diseases in open-access papers, as found by Europe PMC text mining. Sharing a sentence is not in itself a finding about the gene and the disease. The quoted sentences say what the papers report.
depression (257 papers, 2007 to 2026). "Other genetic factors like 5‐HTTLPR and MAOA polymorphism increase the risk of depression by altering the serotonin levels and stress response pathways." (PMID 40387308, 2025). "In this context, variants in the monoamine-degrading enzymes, catechol-O-methyltransferase (COMT) and monoamine oxidase A (MAOA), modulate brain dopamine, norepinephrine, and serotonin levels and functions and have been linked to both depression and obesity." (PMID 41375608, 2025). "Our model supports the assumption that 5-HTTLPR and MAOA exhibit susceptibility properties, consistent with studies on depression, suicide, criminality, and alcohol problems." (PMID 40046992, 2025). "MAOA has been consistently associated with conditions such as addiction, depression, autism, and antisocial behavior." (PMID 39359688, 2024). "A polymorphism in the 59-flanking regulatory region of the MAOA gene has been linked with affective disorders, including depression." (PMID 37374342, 2023). "Excessive menstruation and fluctuating estradiol levels affect the binding of monoamine oxidase A, and increase the risk of severe depression in women by affecting the stress response and emotional regulation in the brain network." (PMID 37065890, 2023). "We were not able to replicate the findings reported for the NR3C1 and MAOA genes, for which DNAm levels were found to explain the maltreatment-depression association." (PMID 36634080, 2023). "Alterations in COMT and MAOA DNA methylation have previously been linked to stress and various stress-related disorders, such as depression and anxiety." (PMID 37185702, 2023). "Although not statistically significant, only patients with at least one MAOA uVNTR 3R allele presented cases of severe depression according to the revised Beck Depression Inventory-II (BDI-II) interpretations." (PMID 37533936, 2023). "KDM1A was associated with seven drugs, and MAOA with six drugs, many of which were monoamine oxidase inhibitors prescribed for depression and hypertension or PPAR stimulators used in diabetes treatment." (PMID 37958805, 2023). "In healthy individuals, a polymorphism in the promoter region of the MAOA gene has been related to the quality of wakefulness, whereas polymorphisms in MAOA have been associated with major depression and with suicidal behavior in men." (PMID 35407454, 2022). "Elevated MAOA activity has been pointed out as a mechanism implicated in depression through producing ROS and catalyzing levels of all the three major monoamines (serotonin, norepinephrine, and dopamine) in the brain." (PMID 34829725, 2021). "Previous research has provided sufficient support to suggest that MAOA gene polymorphism has an impact on depression and impulsivity (which are closely associated with self-injurious behaviors) via the development and functioning of corticolimbic circuits." (PMID 33807669, 2021). "Remarkably, healthy astrocytes treated with chronic cortisol dysregulated genes previously linked with depression including MAOA, which modulates neurotransmitter levels, and neurotrophin signaling gene NTRK2/TrkB." (PMID 34848679, 2021). "Physical abuse was particularly associated with hyper-methylation at CpG7/8, whereas sexual abuse was particularly associated with hyper-methylation of the MAOA first exon as well as an increased risk of current depression." (PMID 34377567, 2021). "Polymorphisms of MAOA have also been implicated in treatment response to mirtazapine among individuals with depression, further highlighting the gene’s clinical importance to understanding etiology and treatment." (PMID 34424394, 2021). "This is an expected finding given previously reported associations of higher exonic methylation and depression diagnoses in a smaller group of the women included in the current study, and further highlights the role of MAOA in depression." (PMID 34424394, 2021).
depression (continued). "The association between the MAOA T941G polymorphsim and behaviors such as borderline personality disorder, placebo responses of patients with major depression, and violent behaviors among prisoners, have been reported." (PMID 30018578, 2018). "The monoamine oxidase-A linked polymorphic region (MAO-A), which alters the degradation serotonin and other amine neurotransmitters, has been related with risk for depression and anxiety disorders in postmenopausal women." (PMID 30544539, 2018). "Although SA was directly associated with all mental disorders examined, hypermethylation of the MAOA first exon mediated the association between SA and current depression, and was directly associated with lifelong depression." (PMID 29600412, 2018). "While the present study consistently showed that hypermethylation of the MAOA ROI was associated with depression, two previous studies of males and females reported hypomethylation in this same region among depressed women." (PMID 29600412, 2018). "Hypermethylation of MAOA first exon mediated the association of SA with current depression, and both methylation levels and SA independently predicted lifetime depression." (PMID 29600412, 2018). "Does MAOA first exon methylation mediate associations of sexual abuse with alcohol dependence, drug dependence, depression disorders, anxiety disorders, and CD?" (PMID 29600412, 2018). "MAOA-uVNTR (monoamine oxidase A-upstream variable number of tandem repeats) polymorphism has been reported to be associated with major depressive disorder by various studies." (PMID 27752275, 2016). "Polymorphisms of the monoamine oxidase A (MAOA) gene have been associated with an increased risk of depression." (PMID 27752275, 2016). "Abnormal regulation of MAOA has been associated with depression, substance abuse, and sexual maturation." (PMID 27610078, 2016). "Future studies with larger sample sizes are needed to detect a possible association between MAOA-uVNTR genotype and orbitofrontal cortex thickness in depression." (PMID 27752275, 2016). "MAOA product is an enzyme known to degrade amine neurotransmitters, such as dopamine, serotonine, epinephrine, and to cause severe depression, but was also shown to be involved in the metabolism of xenobiotics." (PMID 25682200, 2015). "Consistent with this, MAOA has been linked to both aggression and the development and pharmacological treatment of depression." (PMID 23170243, 2012). "We provide evidence for an association between depression in postmenopausal women and the T allele of the MAO-A gene, previously linked to high MAOA enzymatic activity." (PMID 22619623, 2012). "The results of our study showed that the MAOA 4R allele was associated with increased vulnerability to depression among the male subjects in our studied cohorts." (PMID 21605465, 2011). "Polymorphisms of the MAOA gene have been investigated in several psychiatric illnesses including schizophrenia, major depressive disorder (MDD) and bipolar affective disorder (BPD)." (PMID 21978760, 2011). "The MAOA uVNTR polymorphism has been identified as a genetic factor that can modulate the risk for depression, suicide, or both by influencing monoaminergic activity in a sexually dimorphic manner." (PMID 21605465, 2011). "The results of our study demonstrated that the MAOA 4R allele indirectly confers vulnerability to suicide in male patients with depression." (PMID 21605465, 2011). "In contrast to our finding that the MAOA 4R allele was associated with suicide attempts in male patients with depression, the 4R allele was reported to be associated with MDD in German females." (PMID 21605465, 2011). "The MAOA uVNTR polymorphism has been documented to affect the MAOA gene at the transcriptional level and is associated with aggressive impulsive behaviors, depression associated with suicide (depressed suicide), and major depressive disorder (MDD)." (PMID 21605465, 2011).
depression (continued). "Additionally, elevated levels of monoamine oxidase A (MAO-A) are linked to major depression, and ar-turmerone has been shown to exert antidepressant-like effects by reducing MAO-A levels and alleviating stress in a murine model." (PMID 39275058, 2024). "Thus, monoamine oxidase A inhibitors (MAOAIs) have been developed against active MAOA variants and used clinically to treat the symptoms of depression." (PMID 38349393, 2024). "Additionally, MAOA plays a critical role in regulating neurotransmitters in the brain that are closely linked to emotions, including depression, reward, and aggression." (PMID 39359688, 2024). "The upregulation of type A monoamine oxidase (MAOA) and the downregulation of serotonin (5-hydroxytryptamine, 5-HT) and NE levels in the brain are considered to be the primary etiological factors underlying depression." (PMID 38389919, 2024). "Increased monoamine oxidase-A (MAO-A) activity was found in patients with depression and NAFLD, which may be associated with enhanced cellular oxidative stress and adversely affect liver pathology in NAFLD." (PMID 38999812, 2024). "The MAOA single nucleotide polymorphisms (SNPs) rs1137070 (T/C, exonic, in high linkage disequilibrium with rs2064070 (A/T, downstream variant)) and rs6323 (G/T, exonic) have been associated with depression and suicidal symptoms, respectively." (PMID 37322010, 2023). "Ala431 mutations (particularly, Ala431Glu) may play a role in depression by modulating the monoamine oxidase-A (MAO-A) pathway." (PMID 36142879, 2022). "What is more, monoamine oxidase A (MAOA) gene variation is also associated with risk of depression." (PMID 35663561, 2022). "However, deficiency of serotonin can lead to depression, so MAOA and MAOB were two important targets for DD." (PMID 34306154, 2021). "It has been suggested that the susceptibility of MAOA-L females to depression may be a result of epigenetic dysregulation of MAOA by early life stressors, which affects DNA methylation of the glucocorticoid receptor gene NR3C1." (PMID 33584798, 2020). "Our study showed that women with a recessive or overdominant model of MAOA inheritance may be at increased risk of developing depressive disorders." (PMID 33379297, 2020). "One gene that has been linked to symptoms of mental disorders, such as depression and anxiety as well as cognitive abilities, including episodic memory, is the monoamine oxidase A gene (MAO-A)." (PMID 29487517, 2018). "We found that SA was directly associated with CD, depression, and hypermethylation of the MAOA ROI." (PMID 29600412, 2018). "In addition, SA and hypermethylation of the MAOA ROI were independently associated with lifetime depression." (PMID 29600412, 2018). "MAOA exon 1 hypermethylation was shown to mediate associations between SA and current depression." (PMID 29600412, 2018). "We investigated whether methylation in a region spanning the MAOA first exon and part of the first intron was associated with PA and/or SA, MAOA genotype, alcohol dependence, drug dependence, depression disorders, anxiety disorders, and conduct disorder." (PMID 29600412, 2018). "The monoamine oxidase A (MAO-A) gene that encodes the MAO-A enzyme may be also responsible for an inclination to depression." (PMID 27614969, 2016). "The high activity 4R MAOA allele was found to be associated with depression in male subjects." (PMID 21605465, 2011). "The allele of the MAOA uVNTR polymorphism that results in high levels of expression (high activity-related allele) has been reported to be associated in males with suicide caused by depression." (PMID 21605465, 2011). "The results of genetic correlation studies have identified several MAOA gene variants associated with altered MAOA expression levels: Low-activity forms of the MAOA gene are related to aggression and hyperactivity disorders, whereas high-activity forms are associated with depressive disorders." (PMID 38349393, 2024).